IGLV3-22 (immunoglobulin lambda variable 3-22)
Description:
V region of the variable domain of immunoglobulin light chains that participates in the antigen recognition. Immunoglobulins, also known as antibodies, are membrane-bound or secreted glycoproteins produced by B lymphocytes. In the recognition phase of humoral immunity, the membrane-bound immunoglobulins serve as receptors which, upon binding of a specific antigen, trigger the clonal expansion and differentiation of B lymphocytes into immunoglobulins-secreting plasma cells. Secreted immunoglobulins mediate the effector phase of humoral immunity, which results in the elimination of bound antigens. The antigen binding site is formed by the variable domain of one heavy chain, together with that of its associated light chain. Thus, each immunoglobulin has two antigen binding sites with remarkable affinity for a particular antigen. The variable domains are assembled by a process called V-(D)-J rearrangement and can then be subjected to somatic hypermutations which, after exposure to antigen and selection, allow affinity maturation for a particular antigen.
Synonyms: IGLV322; V2-15
Gene: Immunoglobulin variable (V) gene on chromosome 22 (22,704,265 to 22,704,822, forward strand). Ensembl gene ENSG00000211661.
Subcellular location: Secreted; Cell membrane
Gene Ontology:
Biological process: immune response
Cellular component: extracellular region; immunoglobulin complex; plasma membrane
Homologues: Orthologues: tropical clawed frog igl (49% identical). Paralogues in human: IGLV3-25 (76% identical), IGLV3-27 (74% identical), IGLV3-16 (72% identical), IGLV3-10 (71% identical), IGLV3-1 (70% identical), IGLV3-21 (67% identical), IGLV3-9 (67% identical), IGLV3-19 (63% identical), IGLV3-12 (62% identical), IGLV3-32 (61% identical), IGLV6-57 (57% identical), IGLV2-18 (56% identical), and 81 more.
Diseases named in the same sentence as IGLV3-22 in open-access papers:
IGLV3-22 is named in the same sentence as 2 diseases in open-access papers, as found by Europe PMC text mining. Sharing a sentence is not in itself a finding about the gene and the disease. The quoted sentences say what the papers report.
chronic lymphocytic leukemia (1 paper, 2021). "Likewise, IGLV3-21, an important paralog of IGLV3-22, was confirmed to be a risk factor for chronic lymphocytic leukemia." (PMID 34133324, 2021).
IGLV3-22 also shares sentences with these, for which no sentence is quoted: tumor (1 paper).